ALKBH2 (alkB homolog 2, alpha-ketoglutarate dependent dioxygenase)
Description:
Dioxygenase that repairs alkylated nucleic acid bases by direct reversal oxidative dealkylation. Can process both double-stranded (ds) and single-stranded (ss) DNA substrates, with a strong preference for dsDNA. Uses molecular oxygen, 2-oxoglutarate and iron as cofactors to oxidize the alkyl groups that are subsequently released as aldehydes, regenerating the undamaged bases. Probes the base pair stability, locates a weakened base pair and flips the damaged base to accommodate the lesion in its active site for efficient catalysis. Repairs monoalkylated bases, specifically N1-methyladenine and N3-methylcytosine, as well as higher order alkyl adducts such as bases modified with exocyclic bridged adducts known as etheno adducts including 1,N6-ethenoadenine, 3,N4-ethenocytosine and 1,N2-ethenoguanine. Acts as a gatekeeper of genomic integrity under alkylation stress. Efficiently repairs alkylated lesions in ribosomal DNA (rDNA). These lesions can cause ss- and dsDNA strand breaks that severely impair rDNA transcription. In a response mechanism to DNA damage, associates with PCNA at replication forks to repair alkylated adducts prior to replication.
Synonyms: ABH2; MGC90512
Tractability: Small molecule: a structure with a bound ligand is known. PROTAC: ubiquitination databases record sites on it; a small molecule that binds it is known.
Target class: Enzyme; Oxidoreductase
Gene: Protein-coding gene on chromosome 12 (109,088,188 to 109,098,462, reverse strand). Ensembl gene ENSG00000189046.
Subcellular location: Nucleus; Nucleus, nucleolus; Nucleus, nucleoplasm
Subcellular location (Human Protein Atlas): Nucleoplasm; Cytosol; Primary cilium
Pathways (Reactome):
DNA Repair: ALKBH2 mediated reversal of alkylation damage
Gene Ontology:
Molecular function: broad specificity oxidative DNA demethylase activity; cytosine C-5 DNA demethylase activity; ferrous iron binding; protein binding; rDNA binding; 2-oxoglutarate-dependent dioxygenase activity
Biological process: DNA alkylation repair; DNA repair
Cellular component: nucleolus; nucleoplasm; nucleus
Genetic constraint (gnomAD): Loss-of-function variants: 19 observed, 20.02 expected, observed/expected ratio (o/e) 0.95, 90% interval 0.66 to 1.39. The upper end of that interval is the gene's LOEUF score, 1.39, which puts it in group 5 of 6, group 1 being the genes least tolerant of losing a copy. Missense variants: 310 observed, 343.88 expected, observed/expected ratio (o/e) 0.9, 90% interval 0.82 to 0.99. Synonymous variants: 135 observed, 138.74 expected, observed/expected ratio (o/e) 0.97, 90% interval 0.85 to 1.12.
Homologues: Orthologues: chimpanzee ALKBH2 (100% identical), macaque ALKBH2 (98% identical), pig ALKBH2 (84% identical), dog ALKBH2 (80% identical), rabbit ALKBH2 (80% identical), guinea pig ALKBH2 (79% identical), mouse Alkbh2 (75% identical), rat Alkbh2 (72% identical), tropical clawed frog alkbh2 (57% identical), zebrafish alkbh2 (53% identical).
Diseases named in the same sentence as ALKBH2 in open-access papers:
ALKBH2 is named in the same sentence as 20 diseases in open-access papers, as found by Europe PMC text mining. Sharing a sentence is not in itself a finding about the gene and the disease. The quoted sentences say what the papers report.
breast carcinoma (6 papers, 2017 to 2025). "Next, we isolated nuclear and cytosolic extracts containing endogenous ALKBH2 from cultured MDA-MB-231 breast cancer cells to test whether NO could similarly inhibit ALKBH2 derived from biological sources." (PMID 38645113, 2024). "By making use of methylome data for breast cancers and normal breast tissues, we specifically asked whether aberrant CpG methylation events are found over the promoter region of either ALKBH2 or ALKBH3." (PMID 28679371, 2017). "With compared the expression of ALKBH family members in breast cancer and normal samples, the up-regulation was ALKBH1, ALKBH2, ALKBH4, ALKBH6, ALKBH7, and others such as ALKBH3, ALKBH8, FTO was down-regulation." (PMID 35980268, 2022). "This is of particular importance since both ALKBH2 and ALKBH3 have been proposed as tumor suppressors, being silenced in various tumors, including gastric and breast cancer." (PMID 34723799, 2021). "The ALKBH3 gene, but not ALKBH2, undergoes CpG promoter methylation and transcriptional silencing in breast cancer." (PMID 28679371, 2017). "In this study, we demonstrate that the ALKBH3 gene, not ALKBH2, is found recurrently silenced in breast cancer by epigenetic events which, furthermore, defines a group of patients with dramatically reduced survival." (PMID 28679371, 2017). "In contrast, differential methylation between breast cancer and normal breast tissue was not identified over the promoter region of ALKBH2." (PMID 28679371, 2017).
glioma (5 papers, 2010 to 2025). A benign or malignant brain and spinal cord tumor that arises from glial cells (astrocytes, oligodendrocytes, ependymal cells). "It is of interest that ALKBH2 is frequently upregulated in glioblastomas, and patients with high expression levels have a reduced overall survival, supporting this view and suggesting ALKBH2 as a potential prognostic biomarker in gliomas." (PMID 40564198, 2025). "As ALKBH2 is more significantly expressed in the relatively resistant glioma cells, we focused on the molecular process leading to induction of ALKBH2 expression during Ph-PDT and its contribution to PDT resistance." (PMID 20661249, 2010). "The data strongly indicate that ALKBH2-mediated DNA repair is involved in the defense against ART-induced DNA damage and propose ART as a therapeutic supplemental agent notably for IDH1/2-mutated gliomas and presumably also other cancers displaying this mutation." (PMID 40564198, 2025). "It has been shown that overexpression of ALKBH2 in glioma cell lines enhances resistance to TMZ, and conversely, siRNA-knockdown of ALKBH2 increases TMZ sensitivity." (PMID 29844863, 2018).
bladder cancer (4 papers, 2019 to 2026). "Mechanistically, AlkBH2 activates the nuclear factor-kappa B (NF-κB) signaling pathway, which in turn drives the progression of bladder cancer." (PMID 42096412, 2026). "Our findings demonstrate that AlkBH2 promotes the proliferation, colony formation, migration, and invasion of bladder cancer cells." (PMID 42096412, 2026). "For example, APOBEC2 expression in bladder cancer was associated with methylation of the 5′ UTR and the 1st exon of the DNA demethylase ALKBH2, whose product removes N1-meA and N3-meC (ρ = − 0.8687)." (PMID 33676569, 2021). "However, the role of alkyladenine DNA glycosylase homolog 2 (AlkBH2), an enzyme involved in DNA repair and a member of the AlkB family, in the context of bladder cancer inflammation remains largely unexplored." (PMID 42096412, 2026). "A study indicated that ALKBH2 is highly expressed in bladder cancer." (PMID 33744868, 2021). "Likewise, Alkbh2 knockdown in bladder cancer tissue limited tumour development, while ALKBH2 down-regulation sensitized cells to alkylating agents in glioma and cisplatin in lung cancer." (PMID 31519943, 2019).
glioblastoma (4 papers, 2022 to 2025). The most malignant astrocytic tumor (WHO grade IV). "Finally, we demonstrate that the knockout of ALKBH2 causes the sensitization of glioblastoma cells to ART." (PMID 40564198, 2025). "Human α-ketoglutarate-dependent dioxygenase AlkB homolog 2 (ALKBH2) directly reverses these lesions and was reported to contribute to glioblastoma resistance to TMZ." (PMID 39656916, 2025). "We also treated glioblastoma cells with 2-HG, generated ALKBH2 knockout cells, and checked their sensitivity to the cytotoxic effects of artesunate." (PMID 40564198, 2025). "We further revealed that ALKBH2 knockout glioblastoma cells are more sensitive to ART than cells expressing ALKBH2." (PMID 40564198, 2025). "On the other hand, ALKBH2 is highly expressed in human glioblastoma and in established GBM cell lines." (PMID 35053068, 2022). "Both ALKBH5 and ALKBH2 are highly expressed in glioblastoma and this is the reason why we started our experimental validation from these two proteins, while an in-depth analysis and validations for the other top-ranked potential targets will be the matter of future studies." (PMID 35053068, 2022). "ALKBH2 expression levels are elevated in human glioblastoma multiforme (GBM) and established GBM cell lines." (PMID 37007161, 2023). "MV1035 was tested following its in silico predicted ability to act as an inhibitor against ALKBH2 and ALKBH5, both involved in maintaining the tumorigenicity of glioblastoma." (PMID 35053068, 2022).
brain tumors (3 papers, 2015 to 2025). "In addition, ALKBH2 plays a crucial role in the treatment of pediatric brain tumors during chemotherapy." (PMID 33897761, 2021). "Additionally, ALKBH2 has been shown to play an efficient role in pediatric brain tumors during chemotherapy treatment, and the combination of an ALKBH2 knockdown and cisplatin chemotherapy seems to improve the efficacy of treatment." (PMID 25362550, 2015).
colorectal cancer (3 papers, 2020 to 2025). A primary or metastatic malignant neoplasm that affects the colon or rectum. "qRT-PCR assay showed that ALKBH2 expression was higher in all colorectal carcinoma cells compared with normal colorectal epithelial cells." (PMID 33302959, 2020). "However, the role of ALKBH2 in colorectal carcinoma (CRC) remains unclear." (PMID 33302959, 2020).
gastric cancer (2 papers, 2022 to 2024). A primary or metastatic malignant neoplasm involving the stomach. "Conversely, ALKBH2, ALKBH3, ALKBH5, ALKBH6, and ALKBH7 showed low expression in gastric cancer tissues." (PMID 38902235, 2024).
prostate carcinoma (2 papers, 2015 to 2025). A carcinoma that arises from epithelial cells of the prostate gland. "Moreover, our study presents evidence that USP7 stabilizes the demethylation repair proteins ALKBH2 and ALKBH3 in GBM cells, expanding upon previous observations in prostate cancer cells." (PMID 40835840, 2025).
colitis (1 paper, 2021). Inflammation of the colon. "Moreover, in the mice with deficiency in three DNA repair proteins (Aag−/−/Alkbh2−/−/Alkbh3−/− triple-knockout), a single cycle of DSS-induced colitis resulted in absolute lethality of these mice." (PMID 34764977, 2021).
lymph node metastasis (1 paper, 2021). "At the same time, the mRNA expression levels of ALKBH2, ALKBH3, and ALKBH6 had a trend to upper expression in tumors with lymph node metastasis, although this was not significant." (PMID 34150745, 2021).
rhabdoid tumor (1 paper, 2025). An aggressive malignant embryonal neoplasm usually occurring during childhood. "Remarkably, we uncover upregulation of more than 70% of the gene signature in rhabdoid tumor samples as compared to normal kidney, including ALKBH2, which contributes to the direct reversal pathway." (PMID 40647552, 2025).
urothelial carcinoma (1 paper, 2011). A malignant neoplasm derived from the transitional epithelium of the urinary tract (urinary bladder, ureter, urethra, or renal pelvis). "ALKBH2 and ALKBH3 share the ability of E.coli AlkB to directly reverse nucleic acid damage in vitro, and we reported in a recent study that ALKBH8 has important roles in the survival and progression of human urothelial carcinoma both in vitro and in vivo." (PMID 21285982, 2011).
cancer (17 papers, 2012 to 2025). A tumor composed of atypical neoplastic, often pleomorphic cells that invade other tissues. "Overall, the data strongly support the notion that critical lesions induced by ART are repaired by ALKBH2, which is inactive in IDH1mt cancer cells due to 2-HG formation." (PMID 40564198, 2025). "GBM cell lines exposed to the methylating drug temozolomide upregulate ALKBH2 expression levels, and overexpression of ALKBH2 inversely increases cancer cell resistance to temozolomide and methanesulfonate." (PMID 37007161, 2023). "As a dsDNA demethylase, the role of ALKBH2 in cancers is only focused on phenotype, and the pathways by which downstream genes are up or down-regulated are unclear." (PMID 37007161, 2023). "Downregulation of ALKBH2 in human cancers is among pieces of evidence supporting its possible clinical significance, as is the ability to increase sensitivity of cancer cells to chemotherapy." (PMID 35956910, 2022). "On the other hand, ALKBH3 is often overexpressed in different cancers and inhibition of ALKBH2 and ALKBH3 can sensitize cancer cells to alkylating chemotherapy." (PMID 34723799, 2021). "Consistently, ALKBH2 staining demonstrated a higher percentage of ALKBH2-positive cells in CRC tissues compared to para-carcinoma control tissues." (PMID 33302959, 2020). "Downregulation of ALKBH3 resulted in human non-small-cell lung cancer regression, whereas downregulation of ALKBH2 increased the sensitivity of cancer cells to cisplatin, an alkylating-like anticancer drug." (PMID 22291995, 2012). "Knockdown of ALKBH2 then increased the sensitivity of cancer cells to both of these drugs." (PMID 37007161, 2023). "Conversely, the knockdown of ALKBH2 could promote cell cycle progression as well as the growth of cancer cells." (PMID 37007161, 2023). "At least three homologs, ALKBH2, 3 and 8, are affected in various cancers/tumors." (PMID 22291995, 2012). "However, our data also demonstrated that the DNA repair enzyme ALKBH2 was inhibited by NO, which may have implications for cancer etiology and treatment." (PMID 39966373, 2025). "However, in some cancers, the regulation of ALKBH2 is reversed." (PMID 37007161, 2023). "It is currently unknown whether ALKBH2 or ALKBH3 undergo epigenetic silencing in cancer." (PMID 28679371, 2017). "In particular, we noted that cancer-related genes including METTL1, ALKBH2, PSPH, PTPRC, and TRIP13 contributed the most to the identification, which indicated the great biological interpretability of our model." (PMID 38243719, 2024). "The transcript levels and distribution of ALKBH2 in 39 CRC and 33 para-carcinoma tissues were detected by qRT-PCR and immunohistochemistry, respectively." (PMID 33302959, 2020). "We observed unidentified thus far cytoplasmic localization of ALKBH2 and 5 in HNSCC, suggesting abnormal role(s) of ALKBH proteins in cancer." (PMID 31519943, 2019). "In the cancer tissue, we observed a similar correlation involving ALKBH5-FTO, ALKBH3-ALKBH5, and ALKBH1-ALKBH5, but also noted that the level of ALKBH2 was correlated with that of ALKBH5 and ALKBH1 with ALKBH3." (PMID 31519943, 2019). "However, it is currently unknown whether ALKBH2 or ALKBH3 are found inactivated in cancer." (PMID 28679371, 2017). "In contrast, silencing of ALKBH2, 3, 8 or both, ALKBH2 and 3, did not affect cancer cell viability." (PMID 31519943, 2019). "So far, the roles of ALKBH1, ALKBH2, and ALKBH3 in cancer regulation have not been studied much." (PMID 37007161, 2023).
tumor (10 papers, 2018 to 2024). "Further analysis indicated that, among overexpressed ALKBH proteins, the greatest difference between tumour and surrounding tissue was observed for ALKBH2 (5-fold), FTO (4-fold), ALKBH1 (3-fold), and 5 (2-fold)." (PMID 31519943, 2019). "ALKBH2 promotes cell proliferation and is overexpressed in several types of tumor cells." (PMID 36774470, 2023). "Among these genes, PLK1, CDC25C, ESCO2, AXIN2, TREX2, ALKBH2, and MC1R were upregulated in tumor tissues, whereas IGF1 and ESR1 presented downregulation." (PMID 35484177, 2022). "The highest mRNA expression levels of ALKBH2 and ALKBH3 were found in tumor N3 and were significantly correlated." (PMID 34150745, 2021). "Similarly, Fujii and colleague reported the stimulative roles of ALKBH2 on the MUC1, an anti-adhesion molecule, on tumor cell growth." (PMID 34150745, 2021). "In conclusion, rhein inhibited AlkB repair enzymes (AlkB, ALKBH2, and ALKBH3) in vitro and reduced cell resistance to MMS, and it was speculated that ALKBH2 and ALKBH3 enzymes may be effective pharmacological targets for overcoming tumor resistance to methylated anticancer drugs." (PMID 34457021, 2021).
cardiovascular diseases (1 paper, 2023). "As crucial factors involved in the DNA damage and repair process, it would be meaningful to investigate the association between ALKBH2/3 and the cardiovascular diseases induced by DNA-damage-mediated cell death in cardiomyocytes and vascular endothelial cells." (PMID 37612540, 2023). "Few studies focused on the role of ALKBH2 and ALKBH3 in cardiovascular diseases." (PMID 37612540, 2023).
ALKBH2 also shares sentences with these, for which no sentence is quoted: Obesity (2 papers); achondroplasia (1); cervical carcinoma (1); lung squamous cell carcinoma (1); melanoma (1).